CD1D (CD1d molecule)
Diseases named in the same sentence as CD1D in open-access papers (continued):
Sharing a sentence is not in itself a finding about the gene and the disease.
Arthritis (9 papers, 2012 to 2024). Inflammation of a joint. "To assess the role of iNKT cells more directly, we evaluated arthritis development in iNKT cell-deficient (Cd1d−/−) and iNKT cell sufficient (Cd1d+/−) SKG mice." (PMID 29980684, 2018). "Depletion of CD1d+ Bregs exacerbated arthritis in mouse models and reduced responses to treatment with α-galactosylceramide, the iNKT cell glycolipid agonist." (PMID 39346706, 2024). "Anti-CD1d mAb administration in DBA1/J mice or knockout of Vα14-expressing NKT cells in B6 background mice resulted in the development of arthritis with reduced severity after CIA induction, suggesting that Vα14-expressing NKT cells were effector cells in IA." (PMID 33072104, 2020). "Similar to Cd1d−/− SKG mice, antibody depletion of iNKT cells was associated with significantly aggravated arthritis development." (PMID 29980684, 2018). "In contrast to the induction of CD4+ Tregs by Bregs52, which is impaired in the absence of IL-10+ B cells, here, we show that the differentiation of iNKT cells that limit inflammation in arthritis is CD1d-dependent but IL-10-independent." (PMID 29449556, 2018). "NKT cells recognize bacterial glycolipids presented by CD1d, and infection of mice deficient in CD1 with B. burgdorferi led to impaired host defense, increased arthritis severity, and impaired spirochete clearance." (PMID 27857714, 2016). "Here the authors show that, alternatively, Bregs may also present lipid antigens on surface CD1d to induce IFN-γ production from invariant natural killer cells to ameliorate experimental arthritis via IL-10-independent pathways." (PMID 29449556, 2018). "Adoptive transfer of WT, but not TLR4-deficient, iNKT cells promoted antibody-induced arthritis in CD1d−/− mice, suggesting that endogenous TLR4 ligands modulate iNKT cell function in arthritis." (PMID 23028952, 2012). "Furthermore, it was shown that CD1d KO mice exhibited less severe arthritis and that arthritis could only be restored with transfer of NKT cells from WT mice and not with transfer of cells from FcγR KO mice." (PMID 27313578, 2016). "The authors of this study proposed a model where T2-MZP B cells would present α-GalCer via CD1d, inducing the secretion of IFN-γ by iNKT cells, which in turn suppress Th1 and Th17 responses in arthritis." (PMID 33995344, 2021). "A recent study demonstrated a novel mechanism by which Bregs presented CD1d-lipid and induced iNKT cells to secrete IFN-γ, which in turn contributed to the down regulation of Th1 and Th17-adaptive immune responses and murine arthritis amelioration." (PMID 33072104, 2020). "Our data demonstrate that suppression of arthritis by T2-MZP Bregs requires both iNKT cells and CD1d." (PMID 29449556, 2018). "In contrast, T2-MZP Bregs from Cd1d−/− mice failed to inhibit arthritis or to limit Th1/Th17 responses in the recipient WT mice." (PMID 29449556, 2018). "Also, CD1d+ T2-MZP Bregs induced suppressive invariant natural killer (iNKT) cells via CD1d-lipid presentation, then secreted IFN-γ by iNKT cells resulted in the downregulation of Th1 and Th17 immune responses and amelioration of antigen-induced arthritis." (PMID 33936028, 2021). "However, in another antigen-induced CD1d KO/B6 mouse arthritis model, the lack of CD1d-dependent NKT cells induced increased joint inflammation throughout the acute phase of arthritis accompanied by an enhanced arthritogenic Th1 response." (PMID 33072104, 2020).
glioma (9 papers, 2010 to 2024). A benign or malignant brain and spinal cord tumor that arises from glial cells (astrocytes, oligodendrocytes, ependymal cells). "Another subset of T cells, NKT cells, are also under investigation for their presence in gliomas, as their antigen-presenting molecule CD1d expression has been found in glioma patients." (PMID 39452154, 2024). "Retinoic acid upregulates CD1d expression in glioma stem cells in vitro, sensitizing them to NK-mediated cytotoxicity." (PMID 36792722, 2023). "Particularly, CD1d-restricted NKT cells were found to play an important role as immunoregulatory cells within the glioma microenvironment." (PMID 33803885, 2021). "CD1d was expressed on both primary glioma cells as well as endothelial cell glioma tissue sections, which suggest that modalities that selectively target NKT cells may have a significant impact in this malignancy." (PMID 34072042, 2021). "Both the number and expanding potential of type I NKT cells in the blood of glioma patients was comparable to those of healthy controls, and these cells could kill glioma in a CD1d-dependent manner, indicating their normal function." (PMID 31231193, 2019). "The expression of CD1d, an antigen-presenting molecule for NK cells, is common in human glioblastoma but not in glioma stem cells." (PMID 36792722, 2023). "Furthermore, the expanded NKT cells demonstrated significant cytotoxic activity ex vivo against U251 glioma cells, a CD1d expressing cell line, in a Cr51 release assay compared to A172 glioma cells, a CD1d negative cell line." (PMID 30991681, 2019).
Sepsis (9 papers, 2015 to 2025). Sepsis is defined as life-threatening organ dysfunction caused by a dysregulated host response to infection. "KRN was administered to CD1d KO neonates 30 h prior to sepsis induction by CS, as had been done in the C57BL/6 wild-type neonates." (PMID 29720984, 2018). "The only published report to date addressing a link between CD1d-restricted, sulfatide-reactive T cells and sepsis has utilized an experimental mouse model of S. aureus infection." (PMID 26322041, 2015). "It is reported that CD1d blockade prior to sepsis had a positive impact on survival in experimental CLP, which correlated with a decrease in spleen NKT cells and in circulating IL-6 and IL-10." (PMID 26114123, 2015). "Finally, we demonstrated that NKT cell-deficient CD1d KO/SRG3β-actin mice are protected from LPS/d-GalN-induced sepsis, indicating that NKT cells are dispensable for SRG3-mediated sepsis suppression." (PMID 33809795, 2021). "Sepsis-induced tissue injury may also increase, release and/or modify endogenous lipids that can be displayed by CD1d to trigger NKT cell responses." (PMID 26322041, 2015). "CD1d is considered to be an effective recognition receptor of CL, and blocking the binding of CL to CD1d and preventing damage of the lung, liver, and spleen may be an effective means to prevent sepsis from developing into MODS." (PMID 31205588, 2019). "However, in vivo treatment with sulfatide, a CD1d-restricted ligand of vNKT cells, has been demonstrated to attenuate the magnitude of the septic response, thus providing indirect evidence for a protective role of activated vNKT cells in sepsis." (PMID 26322041, 2015). "To further investigate the mechanism that may regulate the increased IFN-γ production observed upon blockade of CD1d activation of NKT cells during sepsis, we compared the expression of IFN-γ mRNA and of specific immune-related miRNAs in splenocytes between samples from the four different groups." (PMID 26114123, 2015). "Recent studies have implicated unconventional, innate-like T lymphocytes, including CD1d- and MR1-restricted T cells as effectors and/or regulators of inflammatory responses during sepsis." (PMID 26322041, 2015). "Evolutionary conservation of CD1d and MR1 recognition across mammalian species makes animal models of sepsis particularly useful for studying NKT and MAIT cells." (PMID 26322041, 2015). "Unlike LPS derived from Gram-negative bacteria that activates TLR4-expressing cells to induce sepsis, glycolipid antigens from Gram-positive pathogens such as group B Streptococci activate NKT cells in a CD1d-dependent manner, ultimately resulting in NKT cell-induced septic shock." (PMID 33809795, 2021). "It is possible that, apart from a higher systemic bacterial burden, alterations in innate immune response mechanisms mediated by blockade of CD1d-dependent activation of NKT cells may play a role in the outcome of pneumococcal pneumonia and sepsis." (PMID 26114123, 2015). "How CD1d contributes to the immunopathology of sepsis is not clear." (PMID 26322041, 2015). "In the current study, we observed neither induction of CD1d+CD5+ Breg, nor any strong modification of the B cell transcriptional profile or phenotype, nor acquisition by B cells of a regulatory function towards T cells after sepsis." (PMID 40155394, 2025). "A mouse study that explored the role of type II NKT cells in SA-induced sepsis showed that immunization of Jα18-/- and CD1d-/- mice with the type II NKT cell specific self-lipid sulfatide conferred CD1d-restricted protection, however they did not track type II NKT cells in vivo." (PMID 33312179, 2020). "In addition, while sepsis induced histologic lung injury in these pups compared to the sham, there was not a protective effect in the KRN-pretreated CD1d KO pups." (PMID 29720984, 2018).
chronic lymphocytic leukemia (8 papers, 2013 to 2026). "Similarly, bispecific antibodies targeting CD40 or CD1d have shown success in preclinical models of hematological malignancies, such as chronic lymphocytic leukemia (CLL) and multiple myeloma (MM)." (PMID 40227601, 2025). "Additionally, retinoic acid and the retinoic acid receptor-α agonist AM-580 was found to induce CD1d expression ex vivo in B-cell CLL cells from patients, promoting activation of cytotoxic invariant natural killer T (iNKT) cells." (PMID 36361536, 2022). "Elevated CD1d expression is detected in CD5+ IL10-producing B cells, called B10 B cells, and is correlated with poorer prognosis in chronic lymphocytic leukemia (CLL), a CD5+ B cell malignancy with B10-like functional properties." (PMID 26537916, 2015). "Typically, B cell chronic lymphocytic leukemia (CLL) cells have low or absent CD1d expression." (PMID 38665921, 2024).
eosinophilia (8 papers, 2014 to 2025). "Mice deficient in CD1d-/- and Jα18-/- iNKT cells showed a decrease in airway hyperresponsiveness and eosinophilia, while the adoptive transfer of IL-4- and IL-13-producing iNKT cells restored the airway inflammation, suggesting that type 2 iNKT cells are responsible for asthmatic inflammation." (PMID 35720287, 2022). "Consistent with previous reports, we observed that CD1d-KO mice, which lack NKT cells, generated impaired airway eosinophilia and PAS staining in OVA models, which were partially compensated by multiple airway challenges." (PMID 31164097, 2019). "Not all investigators, however, have reported that CD1d is required for the development of murine AAD; two groups observed relatively normal allergen-induced airway eosinophilia and/or airway pathology in CD1d-deficient mice, although neither group evaluated whether these mice developed AHR." (PMID 29182669, 2017).
Hepatic steatosis (8 papers, 2011 to 2022). Steatosis is a term used to denote lipid accumulation within hepatocytes. "Given the extremely modest effect of CD1d deficiency on glucose tolerance and hepatic steatosis during high fat feeding, we hypothesized that iNKTs may be more important for other types of metabolic challenges, such as fasting." (PMID 21980475, 2011). "In this study, we revealed CD1d-deficient mice fed with an HFD for 24 weeks had increased body weight gain, lipid accumulation, and hepatic steatosis compared to WT mice fed with an HFD." (PMID 35465315, 2022). "In this analysis we figured out that the CD1d might play protective role in hepatic steatosis stage." (PMID 35465315, 2022). "CD1d KO-HFD and WT-HFD mice exhibited increased body weight gain, liver injury, hepatic steatosis, macrophage cell infiltration, and adipocyte volume relative to WT-NCD and CD1d KO-NCD mice." (PMID 35465315, 2022). "To investigate the role of CD1d in HFD-induced liver steatosis, we fed HFD and NCD to WT and CD1d KO mice (CD1d KO-HFD and CD1d KO-NCD, respectively)." (PMID 35465315, 2022). "Given NKT1 cell activation by phospholipid ligands recognized presented by CD1d, we hypothesized that NKT1 cells are key modulators of hepatic IRI because of the increased frequency of activating ligands in the setting of hepatic steatosis." (PMID 36148239, 2022). "Additionally, we show CD1d knockdown (CD1d KO) in HFD-fed wild-type (WT) mice induced NAFLD, which resulted in weight gain, exaggerated liver injury, and hepatic steatosis." (PMID 35465315, 2022).
prostate carcinoma (8 papers, 2010 to 2025). A carcinoma that arises from epithelial cells of the prostate gland. "Interestingly, this aberrant iNKT activation was reversible by the simultaneous addition of αGalCer and IL-12, which allowed iNKT cells to produce IFNγ in response to these CD1d-expressing prostate cancer cells." (PMID 30298063, 2018). "Interestingly, these primary prostate tumors as well as mouse and human prostate cancer cell lines and human prostate epithelium can express CD1d, permitting direct interaction with iNKT." (PMID 30298063, 2018). "Furthermore, in a TRAMP murine model of CD1d+ prostate cancer, iNKT cells directly and predominantly reduce tumorigenesis, to a greater extent than cytotoxic T lymphocytes." (PMID 29326711, 2017). "The relative abundance of iNKT cells in the TRAMP tumor led us to investigate whether murine prostate cancer cells express CD1d and can activate iNKT cells by CD1d-dependent mechanism." (PMID 20593019, 2010). "To determine whether the CD1d expression on these T-antigen induced prostate tumors would translate into human prostate cancers, we tested a panel of human CaP cell lines." (PMID 20593019, 2010).
psoriasis (8 papers, 2013 to 2024). An autoimmune condition characterized by red, well-delineated plaques with silvery scales that are usually on the extensor surfaces and scalp. "The association between CD161 expressed on NKT cells and CD1d expressed on keratinocytes in psoriasis has been intensely investigated." (PMID 32917058, 2020). "Consistent with these animal studies, patients with inflammatory skin diseases (e.g., atopic dermatitis (AD), allergic contact dermatitis (ACD), psoriasis, and UV-induced skin inflammation) display functional alterations in CD1d-restricted NKT cells." (PMID 36119077, 2022). "Collectively, these studies suggest that CD161+ NKT cells play a central role in the pathogenesis of psoriasis by inducing Th1-type cytokine production in a CD1d-dependent manner." (PMID 36119077, 2022). "For example, CD1d was upregulated in the psoriatic plaques from patients with active psoriasis, while patients with active psoriasis and dyslipidemia exhibited increased CD1b expression in skin." (PMID 30061888, 2018). "An NKT cell line derived from a psoriatic patient was capable of producing IFN-γ when cocultured with CD1d-expressing keratinocytes and induced psoriasis plaque formation when injected into engrafted human skin SCID mice." (PMID 30061888, 2018). "Patterns of CD1d expression are also observed in keratinocytes in vitro and in human skin with psoriasis in vivo." (PMID 24151518, 2013). "Moreover, in psoriatic lesions, the upregulated expression of CD1d in KCs activates NKT cells, leading to increased production of the pathogenic factor IFN-γ, thereby promoting psoriasis progression." (PMID 38596682, 2024). "Another telling finding could be that CD1d-restricted CD161+ NKT cells could release instantly IFN-γ if they encounter the glycolipid antigen presented by CD1d on keratinocytes in psoriasis." (PMID 36233237, 2022). "Moreover, in a mouse model of imiquimod-induced psoriasis, a more severe skin inflammation observed in the CD19−/− mice in comparison to the wild type mice was indicative of the IL-10(+) CD1d(high)CD5(+) Bregs’ role in suppressing the psoriasis-like inflammation." (PMID 33669402, 2021). "Another study also showed that CD1d-expressing keratinocytes could stimulate CD161+ NKT cells to produce a more significant amount of IFNγ, resulting in exaggerated psoriasis." (PMID 36119077, 2022). "Moreover, infusion therapy to psoriatic patients with CD3+CD56+ NKT cells (which likely consist of CD1d-restricted NKT cells) restored CD3+CD56+ NKT cell levels in patient PBMCs, leading to improved skin lesions in severe psoriasis." (PMID 36119077, 2022). "Furthermore, in co-culture with CD1d+ keratinocytes pre-treated with IFN-γ, CD94+/CD161+ NKT cells from psoriasis patients produce large amounts of IFN-γ, which is suppressed by an anti-CD1d antibody." (PMID 32917058, 2020). "The ability of CD1d-positive keratinocytes to activate NKT cells to produce IFN-γ could represent a mechanism that contributes to the pathogenesis of PsA, psoriasis, and other autoimmune skin disorders." (PMID 24151518, 2013).
acute myeloid leukemia (7 papers, 2014 to 2025). Acute myeloid leukemia (AML) is a group of neoplasms arising from precursor cells committed to the myeloid cell-line differentiation. "A significant decrease was observed in the levels of CD1d on monocytes in the PB of acute myeloid leukemia (AML) and acute lymphoblastic leukemia (ALL) patients compared with the healthy controls." (PMID 25009659, 2014). "CD1d is also frequently and strongly expressed on various hematological malignancies such as acute myeloid leukemia (AML)." (PMID 38993780, 2024). "Another report showed that iNKT cells from the infusion of donor lymphocytes efficiently lysed leukemia cell lines and primary acute myeloid leukemia (AML) blasts in a dose- and CD1d-dependent manner." (PMID 36830717, 2023). "In fact, CD1d-TCR interactions are of particular importance in chronic lymphoblastic leukemia, myelomonocytic leukemias, T-cell lymphoma, and acute myeloid leukemia (AML) cell recognition." (PMID 32486268, 2020).
diabetes (7 papers, 2009 to 2024). "The protective role of iNKT cells has been shown in the mouse model for type 1 diabetes [non-obese diabetes (NOD) mouse], as CD1d−/− NOD mice, lacking iNKT cells, have a higher risk and earlier onsets of diabetes compared to CD1d+/+ counterparts." (PMID 29997620, 2018). "These cells are unlikely to be involved in the initiation of the disease given the fact that diabetes has been reported in iNKT cell deficient CD1d KO mice, although they may be implicated in disease severity." (PMID 24788601, 2014). "CD1D is a transmembrane protein involved in the presentation of lipid antigens to T cells and known to contribute to the generation of diabetes, and PSD belongs to a family of intracellular signal transduction proteins known to increase insulin sensitivity." (PMID 19961616, 2009). "α-GalCer-specific activation of iNKT cells protects against diabetes in NOD mice, and such protection has also been shown by CD1d restricted type 2 NKT cells in transgenic mice." (PMID 21143521, 2011). "Overexpression of NKT cells protects transgenic NOD mice from diabetes, whereas a shortage of NKT cells in CD1d knock-out mice leads to exacerbation of type 1 diabetes." (PMID 21143521, 2011). "Finally, upregulation of CD1d expression within the beta cells restores the immunoregulatory function of NKT cells and prevents diabetes in NOD mice." (PMID 21143521, 2011). "Interestingly, CD1d knock-out NOD mice show an exacerbation of diabetes, whereas upregulation of CD1d expression within the beta cells restores the immune regularity function of NKT cells preventing diabetes." (PMID 21483778, 2011).
lung carcinoma (7 papers, 2013 to 2025). "Consequently, lung cancer patients with high levels of this marker on DCs showed a stronger antitumor response, with CD1d expression positively correlated with patient survival, and its level decreasing with the advancement of cancer stages (I–IV)." (PMID 39000502, 2024). "iNKT cells and CD1d expression could be a prognostic factor in lung cancer as well." (PMID 32486268, 2020). "The iNKT cells stimulated with anti-PDL1 antibody-treated APCs showed increased cytolysis of CD1d-negative lung cancer cell lines and K562 in two healthy donors." (PMID 27631416, 2016).